IDH1 (isocitrate dehydrogenase (NADP(+)) 1)
Diseases named in the same sentence as IDH1 in open-access papers (continued):
Sharing a sentence is not in itself a finding about the gene and the disease.
tumor (continued). "Significant differences in the prevalence of potentially targetable genomic alterations (ATM, BRAF, BRCA2, ERBB2, IDH1, PIK3CA, and PTEN) were observed in MTAP-loss tumors and varied according to tumor type." (PMID 38330461, 2024). "At this threshold, TBR uptake predicted IDH1-wildtype tumor tissue with lower specificity than ce-T1 (0.76 vs. 0.79) but much higher sensitivity (0.88 vs. 0.41)." (PMID 39061219, 2024). "Within the training dataset, the variables of IDH1 status, gray matter involvement, calcification, and tumor margin exhibited statistically significant differences between the patients with 1p/19q codeletion and those with intact 1p/19q status." (PMID 38600452, 2024). "NGS of the tumor biopsies from the initial diagnosis and from the relapse from March 2022 revealed that the tumor was IDH1 and IDH2 wild type and harbored an FGFR3-TACC3 fusion." (PMID 39211518, 2024). "Although the selected base editor has the potential to yield further insights into the impact of IDH1 in tumor biology, further refinements will be necessary to enhance its editing precision." (PMID 39605316, 2024). "Univariable and multivariable logistic regressions were used to estimate odds ratios (ORs) for expressing IDH1 mutation and MGMT promoter methylation, based on each patient’s age, sex, ethnicity, histology, tumour location and extent of resection." (PMID 39767640, 2024). "Kinetic, HDX-MS, and crystallography experiments revealed fundamental differences in the catalytic mechanisms of WT and tumor-relevant IDH1 mutants." (PMID 38710674, 2024). "The concentration of D-2HG in IDH1/2 mutant ICC tumor tissues is typically about 250 times higher than that in IDH1/2 non-mutant ICC tumor tissues." (PMID 39273177, 2024). "IDH305 is a potent and selective mutant IDH1 inhibitor that has demonstrated brain exposure in rodents, D2-HG reduction, and efficacy in a patient-derived IDH1 mutant xenograft tumor model." (PMID 39876890, 2024). "Mutations in IDH1 and IDH2 are linked to DNA hypermethylation and impact overall survival (OS) across diverse tumor types." (PMID 39606159, 2024). "The use of Skp2 inhibitors to elevate IDH1 protein levels has been shown to redirect tumor cell metabolism toward a more functional TCA cycle, effectively curbing malignant proliferation." (PMID 39611141, 2024). "However, we recognize that other factors, such as tumor location, grade, IDH1 mutation, edema, and the use of anti-epileptic drugs may influence cognitive outcomes and we therefore suggest that larger sample studies should further explore such a more comprehensive model." (PMID 38834633, 2024). "High tumour staining for each of HMGA2, MUC5AC/6, IDH1, PIWIL2, DNA index, and RPL34 was significantly associated with poorer OS upon multivariable analysis." (PMID 38398089, 2024). "IDH mutations, particularly in IDH1 and IDH2 genes, are mutually exclusive and have significant implications for tumor behavior and patient prognosis." (PMID 38167551, 2024).
tumor (continued). "Preclinical data suggests that IDH1-R132H-specific polypeptide vaccines can induce specific therapeutic T helper cell responses and exhibit efficacy against IDH1-R132H-positive tumours in isogenic MHC human mice." (PMID 38660136, 2024). "Tumours of this family show a diffuse histology with features of malignancy, and are wildtype for histone H3, IDH1, and IDH2." (PMID 39126064, 2024). "To assess the clinical significance of our models, we next investigated the presence of N1IC-like tumor cell populations in IDH1-wild type GBM patient samples." (PMID 39192032, 2024). "MGMTp-met tumors are more prevalent in the left temporal lobe, particularly in patients with GB, an IDH1 mutant tumor, tumors with the proneural gene expression subtype, or frontal lobe tumors missing PTEN deletion." (PMID 38893240, 2024). "Molecular biomarkers, including MGMT methylation, IDH1 and IDH2 mutations, and 1p/19q codeletion, are routinely used for tumor classification in clinical settings." (PMID 39768232, 2024). "Consistent with our analysis that IDH1 loss of function mutations is associated with lower lymph vessel signature, upregulation of PDPN induces lymphangiogenesis and metastasis in tumor." (PMID 38241355, 2024). "The IDH1 and IDH2 genes are characterized by a high rate of gain-of-function mutations across various tumor types." (PMID 39123479, 2024). "Our analysis revealed that FCGR3A and FGL2 expression was significantly correlated with clinical variables such as age, tumor type, WHO grade, histology, IDH-1 mutation, and 1p19q status." (PMID 39629005, 2024). "One featured autologous dendritic cells pulsed with tumor lysate and the other investigated an IDH1 peptide vaccine." (PMID 39337916, 2024). "In summary, we conclude that in both the IDH1 MT human primary tumor cell lines and in the murine model VPA inhibits growth at least partially via inhibition of the mTOR pathway and that the mTOR pathway is involved in downregulation of FASN." (PMID 39149696, 2024). "Although some lncRNAs associated with IDH1 mutations (HOTAIRM1, NCRNA00173, MIR155HG, etc.)are involved in various tumor-associated cellular processes." (PMID 38530810, 2024). "Mutations in the metabolic enzymes IDH1 and IDH2 which are enriched in tumours with a high expression of mitochondrial genes, are potentially therapeutic targets." (PMID 38877653, 2024). "Our study demonstrates that patients with higher tumor histological grades who had received adjuvant radiotherapy exhibited IDH1-mut or presented with TERTp-wt experienced improved OS." (PMID 38893240, 2024). "When wild-type IDH1 is upregulated, it has anti proliferation and proapoptotic effects on OS cells and inhibits tumour metastasis." (PMID 38288377, 2024). "Despite the small sample size of our pilot study (two animals per group), the slightly higher TBRmax and TBRmean values in the IDH1 compared to the IDH1R132H tumor align with clinical findings reported in the literature." (PMID 37982850, 2024). "We isolated five GBM TSs (TS13-20, TS13-64, TS14-08, TS14-15, and TS15-88) from tumor tissues obtained from patients with newly diagnosed IDH1 wild-type GBM and also isolated nECM and tECM from patients." (PMID 38675489, 2024). "The results showed that compared with normal tissues, the mRNA expression of five genes, ACBD5, ATAD1, DHRS4, GRHPR, and IDH1, was significantly up-regulated in tumor tissues." (PMID 38406287, 2024). "Tumor-driving IDH1 mutants catalyze a NADPH-dependent conversion of αKG to the oncometabolite D-2-hydroxyglutarate (D2HG), while typically ablating the conventional reaction." (PMID 38710674, 2024).
tumor (continued). "LAMP coupled with a peptide nucleic acid (PNA) clamping probe has been shown to facilitate the detection of IDH1-R132H in tumor samples within approximately 1 h." (PMID 39596840, 2024). "These tumor markers include IDH1 R132, IDH2 R172, pTERT C228 and C250, H3F3A K27/G34, Hist1H3B K27, and BRAF V600." (PMID 39606159, 2024). "We used matrix-assisted laser desorption ionization imaging mass spectroscopy (MALDI MS) to determine if IDH1R132H-expressing tumors had increased 2HG compared to normal brain and wild-type IDH1 tumor tissue." (PMID 38334611, 2024). "Key biomarkers such as MGMT promoter methylation, IDH1/2 mutations, EGFR amplification, and TERT promoter mutations, etc., are examined for their roles in prognosis, therapeutic response, and tumor classification." (PMID 39767571, 2024). "IDH1/2 mutations were much more common in LGG patients (78%) than in HGG patients (3%), so a correlation of tumor grade and the presence of IDH1/2 mutations was observed." (PMID 39684714, 2024). "With a focus on clinically actionable alterations, all IDH1 and ATM mutations were consistent in both tumor and liquid biopsies." (PMID 39273408, 2024). "In selected cases enrichment of cancer gene mutations, such as copy number gain of MYC and KRAS, and pathogenic variants of IDH1 and STK11, was observed in residual tumor cells following study therapy." (PMID 38689060, 2024). "IHC data for the expression of IDH1 in tumor cells were available for 42 cases and Ki67 were available for all cases." (PMID 37621817, 2023). "Compared to IDH1-wt patients, patients with tumours harbouring IDH1-mut were statistically significantly younger, had better performance status and were more likely to have Grade III tumour and MGMT promoter methylation." (PMID 37341199, 2023). "Recent studies have successfully approached generating adult LGG marked by IDH1 alterations by picking slow-growing tumor cells and separating them from fast-growing normal fibroblasts, that typically outgrow from mixed patient-derived cultures." (PMID 37920169, 2023). "In this in vivo context, the two IDH1 KO clones showed a significant delay in tumour growth and a longer time required to reach the xenograft study's endpoint compared to control cells, with loss of IDH1 leading to increased survival." (PMID 37086156, 2023). "In fact, the tumor size mean was slightly larger in IDH1 mutant group; if the lesion size was the main factor affecting executive functions’ status, one would expect IDH1 mutant group to show more impairment compared to IDH1 wild-type one." (PMID 36970174, 2023). "This provides proof of concept that LAMP is capable of amplifying the IDH1 sequence from tumor lysates." (PMID 37733671, 2023). "This mutant IDH1 tumor appeared to display greater sensitivity to the addition of belinostat than the other cases with wild-type IDH tumors based on both standard magnetic resonance imaging (MRI) and advanced spectroscopic MRI criteria." (PMID 37218937, 2023). "As an important molecular marker, IDH1 mutation in GBM indicates a better prognosis and a potential target for effective treatment, such as targeted immunotherapy for tumor-specific epitopes of IDH1 mutation." (PMID 36837790, 2023). "In this study, we inhibited the production of D2HG in IDH1 mutant tumor using the selective IDH1 inhibitor ivosidenib." (PMID 37741882, 2023). "The correlation between IDH1 positivity and tumor size was statistically significant, but regarding survival, we observed no significance." (PMID 37469494, 2023). "TASL expression levels in tumor tissues of patients with IDH1-wildtype were higher than those of patients with IDH1 mutant patients (P < 0.05)." (PMID 37296415, 2023). "Here, we demonstrate the specific detection of IDH1-R132H from crude tumor homogenates in under an hour using CPNA-LAMP with minimal preanalytical processing and without the use of complex equipment." (PMID 37733671, 2023).
tumor (continued). "In the case of IDH1/IDH2 mutations, further development of the tumor population is directed towards diffuse astrocytoma, anaplastic astrocytoma, or oligodendroglial tumors, while EGFR, CDKN2A/B, and PTEN mutations become early driver events for the GBM." (PMID 35876685, 2023). "IDH1-Vaccine or IDH1-targeting agents including ivosidenib and olutasidenib showed clinical benefit in cancer patients in terms of reduced tumor burden and increased PFS." (PMID 37853413, 2023). "Targeting G6PD and other metabolic regulators, such as pyruvate kinase isozymes M1/M2 (PKM1/2), monocarboxylate transporter (MCT), and isocitrate dehydrogenase 1/2 (IDH1/2), has attracted attention as a potential anti-tumor therapeutic strategy." (PMID 38139067, 2023). "Accordingly, HIF1α was upregulated in cells overexpressing mutant IDH1, in cells treated with exogenous 2-HG, in IDH mutant tumours and in brains of mouse embryos expressing idh1 R132H." (PMID 37296846, 2023). "The interval time between the two operations was also significantly longer in IDH1 mutant tumor patients than in IDH1 wild-type tumor patients." (PMID 36597096, 2023). "Integrating these technologies, we confirm immense spatial heterogeneity in GBM samples compared to IDH1-mutant tumors, characterized by the presence of the mesenchymal tumor cell lineage." (PMID 38077210, 2023). "All five patients were IDH1 wildtype, and four patients (except for G05) were positive for TERT mutations based on analysis of resected tumor tissue." (PMID 37717084, 2023). "Of the 19 IDH1 mutant tumor patients, 14 cases (73.68%) were WHO grade 2, 4 cases (21.05%) were WHO grade 3, and 1 case (5.26%) was grade 4." (PMID 36597096, 2023). "An Italian Phase I-II study analyzed 20 patients with IDH1 wt rGBM, who received DC loaded with autologous tumor lysates, in combination with either TMZ or tetanus toxoid pre-conditioning." (PMID 37568717, 2023). "During tumor engraftment, BT142 cells maintained an endogenous, heterozygous IDH1 mutation and I-2HG production." (PMID 37051530, 2023). "The use of the IDH1 R132H antibody significantly facilitated the diagnosis of IDH1mt tumours in histological sections, even when only scattered tumour cells are present; thus, these cases do not present a diagnostic dilemma in most cases." (PMID 37568909, 2023). "The genetic data included of the IDH1 mutation and MGMT promotor methylation status, while clinical data included age, gender, treatment types, and tumor location." (PMID 36672494, 2023). "Of the 36 IDH1 wild-type tumor patients, the pathology results of the primary surgery diagnosed 31 cases (86.11%) as GBM, 2 cases (5.56%) as WHO grade 2, and 3 cases (8.33%) as WHO grade 3." (PMID 36597096, 2023). "In fact, they performed serial xenografts using cells from the xenografted tumor and were able to propagate the line while retaining the mutant IDH1 status." (PMID 36765553, 2023). "BT32 and BT39 were also characterized by the IDH1 R132H genotype corresponding to the initially determined tumor genotype." (PMID 36835465, 2023). "The protein degradation marker of serum 3-methylhistidine was increased in the mutant IDH1 tumor-bearing mice, whereas it was decreased after ivosidenib treatment." (PMID 37741882, 2023). "When the CT26 tumor cells with IDH1-R132H were transplanted into BALB/c mice, the overall survival was shorter, and the lean body weight decreased faster." (PMID 37741882, 2023). "IDH1 and IDH2 have more than 70% homology, and a recent report found that IDH1/2 is closely related to tumours." (PMID 37108242, 2023).
tumor (continued). "In recent years, beyond the molecular factors (i.e., MGMT and IDH1/2), circulating markers of inflammation and immune components within the tumor tissue have been the focus of attention in oncology as potential prognostic factors." (PMID 37584750, 2023). "Five patients had both genetic markers expressed, two thirds of patients with IDH1-mut also had MGMT-met expressed, and among patients with expressed methylation, IDH1-mut tumours were present in 27% of patients." (PMID 37341199, 2023). "More directly, extracellular anti-IDH1 antibody significantly increased GL26-IDH1R132H killing by CTL from tumor-vaccinated mice after 4 h." (PMID 37161052, 2023). "This demonstrated the challenge of generating Idh1-KI mice that express mutant IDH1 protein exclusively in the brain and can be crossed with tumor-prone mice." (PMID 36765553, 2023). "For the pseudotype infection experiments, we collected tumor samples from GBM patients with IDH-1 wild-type and isolated cells from these tumors." (PMID 36901897, 2023). "Elevated TMUB1 expression is linked to unfavorable clinical features such as higher WHO grades, advanced age, larger tumor size, and wild-type IDH1/2 status." (PMID 38148953, 2023). "Combined single-cell RNA and T cell receptor sequencing revealed that tumor-infiltrating T helper cell clusters in a patient with pseudoprogression were dominated by a single IDH1(R132H)-reactive T cell receptor." (PMID 37509387, 2023). "In this study, we investigated the use of a nucleic acid extraction free CPNA-LAMP assay to specifically and rapidly amplify IDH1-R132H mutant DNA in patient-derived tumor samples." (PMID 37733671, 2023). "For histopathology confirmation and diagnosis, MGMT gene methylation, and IDH-1/-2 status, the tumor biopsies were sent to the sites’ hospital pathology laboratory." (PMID 37137304, 2023). "Cachexia group showed low phosphorylation level of mTOR, p70s6k, and 4E-BP1, especially the mice bearing IDH1-mutant tumor." (PMID 37741882, 2023). "EGFRvIII, CMV pp65, TERT, IDH1, surviving, WT1 have been used as single-antigen peptide and include epitopes of tumor-associated or GBM-specific antigens." (PMID 36874119, 2023). "Here we describe tumor-immune interactions through transcriptional and molecular phenotypes/oncogenic pathways and IDH1/2 status." (PMID 37345193, 2023). "By detecting specific genetic mutations, such as IDH1 or EGFR, and monitoring levels of circulating tumor DNA, liquid biopsy can aid in the early detection and monitoring of disease progression." (PMID 37525780, 2023). "This scoring system includes age, tumor grade, LGG diagnosis type, tumor type (primary and recurrence), IDH1 (R132) mutation status, and the risk score of m6A regulator-related AS events." (PMID 35937991, 2022). "It was also interesting to note that IDH1 was differentially expressed across regions of the GBM tumor." (PMID 35877430, 2022). "The univariate cox regression analysis reveals that patients’ clinical characteristics such as age, tumor malignancy grade, and IDH1 status, as well as the expression of miR-181a, are significantly associated with patient overall survival (OS)." (PMID 36232448, 2022). "The direct relationship between the activity of transketolase in the peritumoral zone of the tumor and IDH1 was found with the local clustering coefficient between IDH1 and transketolase −0.637." (PMID 35625744, 2022). "In this study, PLEKHM3 was significantly downregulated in GBM compared to non-tumor, and its expression and methylation were negatively and positively correlated, respectively, with IDH1 expression." (PMID 35877430, 2022).